POLE (DNA polymerase epsilon, catalytic subunit)
Diseases named in the same sentence as POLE in open-access papers (continued):
Sharing a sentence is not in itself a finding about the gene and the disease.
endometrial cancer (continued). "No case fell into the MMR-deficient or POLE-mutant group; in this regard, these molecular groups are less common in ovarian carcinoma than in endometrial carcinoma." (PMID 38418687, 2025). "In the three cancer types studied, colorectal cancer, endometrial cancer, and ovarian cancer, TMB was significantly higher when the corresponding POLE ExoD driver mutation was present in conjunction with one or more additional POLE variant(s)." (PMID 38282550, 2024). "Among the 146 patients with endometrial cancer (EC), 8 patients (5.5%) exhibited the POLE hypermutant type, 29 patients (19.9%) displayed the MSI-H type, 94 patients (64.4%) presented the low copy-number type, and 15 patients (10.3%) manifested the high copy-number type." (PMID 39902126, 2024). "Based on the results of the comprehensive genetic analysis of endometrial cancer, The Cancer Genome Atlas Research Network classified endometrial cancer into four molecular phenotypes (polymerase epsilon [POLE]-ultramutated, MSI-hypermutated, copy number high, and copy number low)." (PMID 38893118, 2024). "This illustrates that the presence of a POLE mutation variant alone is not sufficient for classifying an endometrial carcinoma as POLE-mutated, let alone as pathogenic." (PMID 39239272, 2024). "In 2013, the TCGA published its seminal paper that, based on a multi-omic study, distinguished four main molecular subtypes of endometrial carcinomas: POLE (DNA Polymerase Epsilon) ultramutated, microsatellite instability hypermutated, copy-number low, and copy-number high." (PMID 39001520, 2024). "Somatic mutations within the exonuclease proofreading domain (EDM) of the DNA polymerase Pol ε (POLE) gene are increasingly being discovered in ovarian, colorectal, urological, and, especially, endometrial carcinoma (EC), where these are found in up to 10% of the cases." (PMID 39239272, 2024). "In an effort to subclassify endometrial cancer, The Cancer Genome Atlas (TCGA) Program identified four distinct molecular subtypes of endometrial cancer: Polymerase ε (POLE) ultramutated, microsatellite instable (MSI) hypermutated, copy-number-low (CN-low) and copy-number-high (CN-high) cases." (PMID 37568650, 2023). "POLE is a critical biomarker for endometrial cancer (ECs) prognosis and therapeutic decision." (PMID 38023184, 2023). "Notably, tumors with a high tumor mutational burden, such as POLE and MSI-H endometrial cancers, have higher rates of TILs." (PMID 37568665, 2023). "Agreeing with an earlier, smaller cohort of endometrial cancer patients, they show that tumors with pathogenic POLE variants confer a survival benefit regardless of treatment." (PMID 37388540, 2023). "Further, the molecular classification of endometrial cancer, that is, polymerase epsilon (POLE) ultramutated, MSI hypermutated, copy-number (CN) low, and CN high, not only identifies prognosis but may also guide therapy." (PMID 37835582, 2023).
endometrial cancer (continued). "The presence or absence of POLE mutation allows for a reduction in both over-treatment and under-treatment and to better delineate the prognosis of endometrial cancer." (PMID 37958329, 2023). "Recently, the TCGA proposed four distinct endometrial cancer molecular subgroups based on mutational burden, microsatellite instability and copy number alterations observed in 373 endometrial cancer cases: copy number high, copy number low, MSI hypermutated, and POLE ultra-mutated." (PMID 35530346, 2022). "Of note, there were no patients with POLE-mutated endometrial cancer in the TMB-H group in the GARNET trial." (PMID 35158899, 2022). "The prognostic value of the TCGA classification as applied to uterine carcinosarcoma showed that POLE-mutated carcinosarcomas have an excellent prognosis, similar to that of non-carcinosarcoma endometrial cancers." (PMID 36139624, 2022). "Although our study did not include data on mutations, the POLE mutation has been reportedly observed in approximately 10% of endometrial cancers with ARID1A alteration." (PMID 34257552, 2021). "We showed that mutations in POLE (OR = 0.9690, 95% CI = 0.9422–0.9959, p value = 0.0243) and POLD1 (OR = 0.9573, 95% CI = 0.9223–0.9925, p value = 0.0177) were both more prevalent in younger endometrial cancer patients." (PMID 33879792, 2021). "Indeed, when we excluded tumours with MSI-H and tumours containing POLE/POLD1 mutations from the analysis, we found a significant positive association between mutation burden and age in endometrial cancer (adj." (PMID 33879792, 2021). "Finally, there is fact that a large proportion of endometrial cancer is associated with a hypermutator phenotype, mainly due to MSI (microsatellite instability) and POLE (DNA polymerase epsilon) mutations." (PMID 34670536, 2021). "Despite the existence of a simplified classification, the Proactive Molecular Risk Classifier for Endometrial Cancer (ProMisE), this molecular classification is not implemented in all centers due to the technical complexity of analyzing the POLE mutations." (PMID 34680205, 2021). "Other interesting findings from the NGTS were: (i) frequent detection of RNF43 mutations in both dVIN and de-VIL, which have been previously associated with endometrial carcinoma, and (ii) detection of mutations in KEAP1, CDH1, PIK3R1, and POLE exclusively in de-VIL." (PMID 33918187, 2021).
endometrial cancer (continued). "Large-scale molecular analysis of endometrial tumors grouped endometrial cancers into four molecular classifications: POLE-ultramutated, microsatellite instability-hypermutated, copy-number low (also called endometrioid-like) and copy-number high (also called serous-like)." (PMID 32854222, 2020). "Multiple studies have found significantly improved survival in patients with POLE mutated endometrial cancers, while the survival benefit was not as profound in POLE mutated colorectal carcinoma." (PMID 32838755, 2020). "Both POLE and POLD1 have been associated with an increased risk of endometrial cancer and furthermore POLD1 has been associated with breast and brain tumors in addition to CRC and endometrial cancer." (PMID 32258104, 2020). "In colorectal and endometrial carcinoma, it was well demonstrated that MMR-D or POLE exonuclease domain mutation could lead to a marked increase of somatic mutations in tumors and predict response to anti-PD-L1 treatment." (PMID 32698386, 2020). "In addition, somatic mutations have also been reported to be significantly associated with the prognosis of endometrial cancer such as MUC16 mutations and POLE exonuclease domain mutations." (PMID 31864301, 2019). "In order to further study the function of POLE mutations in cellular metabolism through glucose metabolism, we analyzed the expression levels of 20 genes in glucose metabolism and 18 genes in glycolysis in endometrial cancer samples between the POLE mutant and the wild type." (PMID 31864301, 2019). "Importantly, there are clinical anecdotes of responsiveness to PD-1 inhibition in POLE mutant endometrial cancer and more recently in POLE mutant colorectal cancer." (PMID 28492495, 2017). "An extreme example of this phenomenon is endometrial cancer (EC), where patients with mutations in POLE, encoding a DNA proofreading enzyme, have 105-fold more predicted neoantigens than POLE non-mutated EC." (PMID 27192170, 2016). "In addition to dMMR, inactivating POLE mutation, found in CRC, endometrial cancer, and gastric cancer, can result in an extremely high mutation burden." (PMID 27012666, 2016). "However, endometrial cancers with MMR-D were reported to have lower TMB and neoantigen loads than those with POLE mutations, which might explain the difference in prognosis between the two groups." (PMID 36797358, 2023). "Interestingly, the POLE mutated group show good prognosis regardless of clinicopathological features, which not uncommonly are worrisome; for instance, about half of POLE-mutated endometrial carcinomas are high-grade." (PMID 35892892, 2022). "Assuming an unbiased distribution and a POLE mutation prevalence of 10% in unselected endometrial carcinomas based on 12.2% reported in a large retrospective cohort, from which 82% are now considered pathogenic mutations, we estimated that approximately 8/78 IR/HIR cases would harbor POLE mutations." (PMID 34596362, 2022).
endometrial cancer (continued). "We were unable to recategorize our endometrial cancer cases according to The Cancer Genome Atlas as POLE mutation analysis is not yet available in every-day cancer diagnostics and microsatellite instability (MSI) status was not analyzed in the primary diagnostics in our patient group." (PMID 34054515, 2021). "Of these, one of the non-cancer controls and two non-hypermutated endometrial cancer samples each had one exonic variant (p.Asn1396Ser or p.Leu2274Val, rs5744934 or rs148788180, respectively) mapping to the POLE catalytic domain but both are reported benign in ClinVar." (PMID 33256706, 2020). "Furthermore, it separates serous carcinoma from hitherto unknown types of clinically low-grade endometrial carcinomas that can morphologically mimic serous carcinoma to a substantial degree (eg, POLE, MMR-D)." (PMID 30550484, 2019). "First, POLE mutation testing, utilized for molecular classification of endometrial cancer, was not performed; however, POLE testing may not be cost-effective for daily routine practice." (PMID 30134578, 2018). "In the respective endometrial carcinoma TCGA PanCancer Atlas study, which included 509 cases with complete mutations and copy number alterations information, among the 27 cases with CTCFL mutations 22 had mutations in one of the four MSI associated genes or the POLE or POLD1 genes." (PMID 30275357, 2018). "The apparent difference in tumour spectrum between carriers of the POLE p.Leu424Val and the POLD1 p.Ser478Asn substitutions was unexplained and the authors mention that similar differences are found in Lynch syndrome where endometrial cancer seems to be more frequent in carriers of MSH6 mutations." (PMID 24788313, 2014). "The potential targets for targeted treatment of endometrial cancer (KRAS, PIK3CA, MLH1, MSH6, POLE, PTEN) showed more significant changes in the supernatant of vaginal lavage fluid." (PMID 41602422, 2026). "Immunotherapy has redefined treatment paradigms in endometrial cancer, particularly for molecularly defined subgroups such as MSI-H and POLE-mutant tumors." (PMID 41583426, 2025). "Simultaneously, the two types of EC were classified according to the four TCGA molecular subgroups of endometrial cancer (CN-high, CN-low, MSI, and POLE)." (PMID 37583914, 2023). "Using a high-grade endometrial carcinoma patient cohort, NaroNet found, among other TMEs that could be explored, a local phenotype expressing CD8, PD1, and FOXP3 whose high abundance was associated with the POLE mutation, while achieving a prediction accuracy of 93.75%." (PMID 35217454, 2022).
endometrial cancer (continued). "Anticipating the future incorporation of The Cancer Genome Atlas (TCGA) classification system into endometrial cancer diagnosis and prognostication, it remains uncertain whether grading will remain an important clinical discriminator for tumors, especially in the polymerase E (POLE) category." (PMID 30550484, 2019). "With this approach we provide a rationale for the administration of checkpoint inhibition strategies in subsets of POLE-mutant and MSI endometrial cancer patients." (PMID 28344870, 2017). "MSI-H and POLE EDM mutations were linked to lower HRD scores (P<0.001), showing a negative correlation in ovarian, colorectal, stomach, and endometrial cancers." (PMID 40420266, 2025). "Consistently, endometrial cancers showed elevated POLE transcript levels in comparison to normal tissues." (PMID 38238314, 2024). "In other words, as the POLE signature was not available for all endometrial cancer patients in our centers, a retrospective calculation of the prevalence of the POLE signature (and subsequently of the NSMP signature) was not feasible." (PMID 37958382, 2023). "The role of POLE and POLE mutants in carcinogenesis and the progression of endometrial carcinoma is not fully clear." (PMID 31864301, 2019). "In univariate and multivariate analyses, POLE mutations and MSI status was significantly associated with progression-free survival (P = 0.0129 and 0.0064, respectively) but not with endometrial cancer-specific survival." (PMID 29659608, 2018). "However, a high POLE expression in endometrial cancer patients did not correspond to improved survival compared to those with low POLE expression." (PMID 38238314, 2024). "Non-estrogen-related endometrial carcinoma (NEEC) vs. estrogen-related endometrial carcinoma (EEC) was low in polymerase epsilon (POLE) (OR = 0.49), microsatellite instability (MSI) (OR = 0.45), and copy number low (CNL) (OR = 0.11), while it was high in CNH (OR = 26.76)." (PMID 39839791, 2024). "The study from Haraldsdottir supported the hypothesis of the coexistence of somatic MMR alterations with somatic mutations in DNA polymerase POLE or POLD1 in patients with hypermutated colon and endometrial cancers without germline MMR mutations." (PMID 32258104, 2020). "To understand whether POLE mutations that are not classified as drivers (POLE Variant) contribute to mutagenesis, we assessed TMB in 447 POLE-mutated colorectal cancers, endometrial cancers, and ovarian cancers classified as TMB-high ≥10 mutations/Mb (mut/Mb) or TMB-low <10 mut/Mb." (PMID 38282550, 2024).